ITIH5 (inter-alpha-trypsin inhibitor heavy chain 5)
Diseases named in the same sentence as ITIH5 in open-access papers (continued):
Sharing a sentence is not in itself a finding about the gene and the disease.
tumor (continued). "We have now shown in our study that ITIH5 can also be a prognostic marker in CCA tumor tissue." (PMID 39518085, 2024). "Our hypothesis is that ITIH5 expression is initially upregulated by ITIH5 promoter DNA hypomethylation and potentially later downregulated again during tumor progression." (PMID 39518085, 2024). "This may suggest an initial upregulation of ITIH5 in the early tumor stages, possibly as a protection mechanism of the organ by taking advantage of its tumor suppressive effects." (PMID 39518085, 2024). "This may lead to the hypothesis that the prevention of perineural invasion could be a mechanism of ITIH5`s tumor suppressive action in CCA." (PMID 39518085, 2024). "ITIH5 inhibits tumor growth and metastasis especially by modulating TGF-β signaling." (PMID 39198923, 2024). "Thus, our data suggest the substantial role of the ITIH5-specific VIT domain in ITIH5-mediated suppression of tumor cell proliferation." (PMID 35158755, 2022). "Thus, our findings highlight polypeptides covering the VIT domain as a basis for the development of novel biological drugs potentially able to reactivate ITIH5 specific tumor-suppressive pathways in human cancers." (PMID 35158755, 2022). "Moreover, ITIH5 is the only member of the ITI genes that are inactivated by epigenetic mechanisms which substantially trigger tumor development, plasticity and metastasis." (PMID 35158755, 2022). "In the present study, we confirmed ITIH5-mediated tumor cell growth inhibition in vivo." (PMID 35158755, 2022). "Next, we provided evidence that the VIT domain of the ITIH5 protein administered extracellularly to cancer cells in vitro may make an important contribution to the inhibition of tumor cell growth observed in vivo." (PMID 35158755, 2022). "In summary, we revealed, for the first time, the specific tumor-suppressive function of the ITIH5 VIT domain, but it seems difficult to assess whether the VIT sequences of heavy chains in general mediate tumor growth inhibition." (PMID 35158755, 2022). "This way, it may be possible to restore the tumor-suppressive functions of ITIH5 in cancer cells of various tumor entities that have lost their endogenous ITIH5 expression during tumor progression." (PMID 35158755, 2022). "Since Weidle and colleagues proposed the vision of an ITI-derived protein approach suitable for developing novel anticancer therapies, our study may present a way to restore the tumor-suppressive function of ITIH5 in a much smaller polypeptide." (PMID 35158755, 2022). "This prompted us to further investigate whether truncated ITIH5 proteins applied extracellularly to tumor cells could suppress tumor growth in various cancer entities." (PMID 35158755, 2022). "Increasing evidence indicates that ITIH5 plays a key tumour-suppressive role in various cancers." (PMID 33935281, 2021). "In human PDAC, loss of ITIH5 may be an early event and ITIH5-low PDAC cells in primary tumours may be selected for liver metastasis." (PMID 33024269, 2021). "This could be a limitation of IHC quantification, or it may be that while ITIH5 transcription is reduced in more aggressive tumours, turnover of ITIH5 protein may be less dynamic and would thus fail to show a similar reduction." (PMID 33024269, 2021). "Thus, we gain further insights into the putative role of ITIH5 as tumor suppressor highlighting an impact on drug response potentially via the HA-CD44 axis in BASQ-type BLCA." (PMID 33924987, 2021). "Moreover, cell sphere formation ability, the number of cells penetrated the membrane, resistance to gemcitabine, and the tumor volume were suppressed by ITIH5 overexpression in the PANC-1 stem cells (p < 0.05)." (PMID 34446696, 2021). "We hypothesized that the identified shift in DNA methylation pattern influences expression of genes contributing to the ITIH5 induced, tumor suppressive phenotype of MDA-MB-231 cells." (PMID 28231808, 2017).
tumor (continued). "In addition, only DKK3 and ITIH5 methylation showed a significant concordance in tumor tissue and paired serum specimens." (PMID 23320751, 2013). "ITIH5 expression was decreased in all tumours samples relatively to normal tissues." (PMID 19809427, 2009). "On the other hand, ITIH5 downregulation may be an essential mechanism in thyroid tumourigenesis, especially in tumour metastasis." (PMID 19809427, 2009). "The correlation of ITIH5 expression and the clinical pathological parameters of our CCA cohort applying the Fisher’s Exact Test revealed significant associations between ITIH5 expression and the tumor type, tumor size, number of lesions, vascular invasion, perineural invasion and UICC tumor stage." (PMID 39518085, 2024). "Thus our in vivo data complement the already existing view of ITIH5 as a potent tumor suppressor gene involved in regulating various hallmarks of cancers, i.e., tumor progression and tumor growth, as both functions may be important for the early stages of tumor development." (PMID 35158755, 2022). "ITIH5, a member of the inter-α-trypsin inhibitory (ITI) gene family, acts as a putative tumour-suppressor gene in many cancers." (PMID 33935281, 2021). "Collectively, this study identifies the tumor suppressive activity of LINC00261 in PC, showing that this lncRNA limits the functions of PC stem through an ITIH5/GATA6 regulatory pathway." (PMID 34446696, 2021). "When ITIH5 levels in PDAC tumours were compared to normal pancreatic duct, staining intensity was lower in both primary and metastatic tumours, as well as uninvolved normal pancreatic duct." (PMID 33024269, 2021). "ITIH5 and ECRG4 have been previously identified as putative class II tumor suppressor genes, which are epigenetically silenced in various tumor entities." (PMID 32046186, 2020). "When MSP was applied to tumour samples, a significant reduction of HOXD10, FGFR2 (P < 0.05), ITIH5 and RASAL3 (P < 0.001) promoter methylation was observed in DEC-treated mice." (PMID 30533020, 2018). "ITIH5 and DKK3 proved to be candidate genes showing a significant correlation of the methylation pattern in paired tumor tissue DNA and cfDNA." (PMID 23320751, 2013). "This is important since CCA is the first tumor entity described in which ITIH5 is upregulated rather than downregulated in the tumor compared to normal tissue." (PMID 39518085, 2024). "We compared the homology of the VIT sequence of heavy chains 1–4 with that of ITIH5, determining a range between 26% and 37% only; thus, the ITIH5 VIT domain and its functional role in tumor suppression might indeed be heavy-chain-specific." (PMID 35158755, 2022). "Expression of ITIH5 correlated with decreased cell motility, invasion and metastasis without significant inhibition of primary tumour growth." (PMID 33024269, 2021). "Regardless of our incomplete knowledge of ITIH5 mechanism of action, the data reported here affirm the potential relevance of ITIH5 as a biomarker for assessing tumour progression, metastasis and clinical outcomes for PDAC." (PMID 33024269, 2021). "We did not, however, observe a further reduction in the levels of ITIH5 in metastatic lesions compared to primary tumours." (PMID 33024269, 2021). "As luminal T47D cells already grow in epithelial-like clusters, it makes sense that ITIH5 did not trigger a similar effect in those already well-differentiated tumor cells." (PMID 28231808, 2017). "Furthermore, ITIH5 and DKK3 methylation achieved 40% sensitivity with a high specificity in healthy and benign disease controls." (PMID 23320751, 2013). "In agreement with this, the ITIH5 gene, which may have an essential function in cell attachment and invasion, was under-expressed in PDTC tumours." (PMID 19809427, 2009).
tumor (continued). "Indeed, CCA is the first tumor entity described in which ITIH5 is upregulated rather than downregulated in the tumor compared to normal tissue." (PMID 39518085, 2024). "Recently, it was surprisingly found that the ITIH5 protein is specifically upregulated in CCAs and that ITIH5 detection in blood could be an excellent liquid biopsy marker for indicating the presence of a CCA tumor in a patient." (PMID 39518085, 2024). "Since extracellularly administered ITIH5-derived polypeptides covering the VIT domain could mimic the growth-inhibitory effects of the native ITIH5 protein in a set of different cancer cell lines, our data suggest a substantial role of the VIT domain in restoring tumor suppressive function of ITIH5." (PMID 35158755, 2022). "As metastases were almost exclusively found in lungs of mice injected with cancer cells lacking ITIH5 expression, impaired tumor initiation capabilities could be suggested, a feature mainly attributed to CSC." (PMID 28231808, 2017). "In addition, ITIH5 has been proven to be a novel prognostic marker in invasive node-negative breast cancer, demonstrating its involvement in tumor progression, invasion, and metastasis." (PMID 18226209, 2008). "However, looking at expression patterns of the different heavy chain genes, there may be redundancy in their tumor suppressive functions, as e.g. ITIH2 and ITIH5 are both abundantly expressed in normal breast tissue." (PMID 18226209, 2008). "Tumors with high ITIH5 expression correlate with the diagnosis of iCCA, the absence of perineural invasion and a lower UICC tumor stage." (PMID 39518085, 2024).
cancer (20 papers, 2014 to 2025). A tumor composed of atypical neoplastic, often pleomorphic cells that invade other tissues. "In all cancer tissues analyzed so far, the downregulation or loss of ITIH5 was shown to be caused by promoter DNA hypermethylation and was associated with unfavorable prognosis in most cases." (PMID 39518085, 2024). "It has been consistently shown that the cause of this loss of expression is primarily DNA hypermethylation of the ITIH5 promoter in cancer cells." (PMID 39198923, 2024). "Originally metastatic cancer cells underwent an epigenetic shift driven by ITIH5 that cause a distinct signature of expressed genes." (PMID 28231808, 2017). "ITIH5 is a secreted protein whose loss of expression has been described in many different cancers." (PMID 33024269, 2021). "Additionally, we demonstrate reduced ITIH5 levels in human primary PDAC and matched metastases, suggesting that loss of ITIH5 is an early event in PDAC cancer progression." (PMID 33024269, 2021). "In cancer cell models, the forced overexpression of ITIH5 often slows down cellular characteristics that constitute the hallmarks of cancer, i.e., triggering a reduction in cell proliferation, migration and invasion." (PMID 39518085, 2024). "In turn, overexpression of ITIH5 has been shown to block cancer cell growth, migration and invasion in vitro." (PMID 35158755, 2022). "Namely, Inter-α-trypsin inhibitor heavy chain 5 (ITIH5) is epigenetically altered in various cancers, including BC." (PMID 35158756, 2022). "In fact, it was found that ITIH5 ́s vault protein inter-alpha- trypsin (VIT) domain (approximately 125 amino acids long) can specifically impair the growth of human cancer cells." (PMID 35158755, 2022). "Apart from that, the impact of ITIH5 on anti-cancer treatment remained elusive although CD44 and distinct splice variants have been intensively studied, highlighting an impact on cellular responsiveness to chemotherapeutics." (PMID 33924987, 2021). "Interestingly, ITIH5 exhibited relatively higher expression levels averaged across all cancer types compared to ITIH1-ITIH4, whereas in LIHC, it showed the lowest expression level." (PMID 33744857, 2021). "Given the proposed ITIH5-HA-C44 axis as main mechanism of cancer cell suppression, our data provide a rational why ITIH5 might be predominantly down-regulated in basal-type cancers, i.e., in those tumors known to be characterized by abundant CD44 expression." (PMID 33924987, 2021). "Interestingly, over-represented gene annotations confirmed an impact of ITIH5 expression on biological processes (BP) such as “lipid catabolic process” in this metastatic MDA-MB-231 cancer cell line that is in line with recently published data." (PMID 28231808, 2017). "Moreover, ITIH5 drives an epigenetic reprogramming that reverses the aggressive phenotype of basal-like MDA-MB-231 cancer cells to an epithelial-like phenotype involving re-expression of the well-known tumor suppressor gene DAPK1." (PMID 28231808, 2017). "Therefore, to develop a suitable biological drug for this field of application in the future, the ITIH5 protein may still need to be truncated, modified or stabilized, as has also been proposed for its possible use in personalized cancer therapy." (PMID 39198923, 2024). "Finally, we performed migration studies based on a wound healing assay to give some initial insights into whether truncated ITIH5 polypeptides could also impair the progressive features of cancer cells." (PMID 35158755, 2022). "This component features COL10A1, ITIH5, ADIPOQ, ADAMTS5, GPC3, SFRP1, and RARRES2 genes, pointing to their involvement in cancer-related cellular structures." (PMID 38253993, 2024). "Accordingly, we found significantly negative correlations between ITIH5 and the other four genes using the pan-cancer expression data." (PMID 33744857, 2021). "Interestingly, ITIH5 and SEMA6D were reported as contributors to cancer cell metastasis." (PMID 34921655, 2022).
cancer (continued). "Given that, truncated ITIH5 polypeptides, especially ITIH5161aa may constitute the basis for developing of biologicals to treat human cancers lacking endogenous ITIH5 expression, thus helping to effectively block tumorigenesis." (PMID 35158755, 2022). "ITIH5, on the contrary, demonstrated the lowest expression in the liver and it showed a significantly negative correlation with ITIH1-ITIH4 in pan-cancer datasets." (PMID 33744857, 2021). "We found that, apart from ITIH5, ITIH1-ITIH4 were all robustly expressed in liver hepatocellular carcinoma (LIHC) and cholangio carcinoma (CHOL), with no or low expression in other cancer types." (PMID 33744857, 2021). "Not surprisingly, similarity among different cancer types was identified in only 6 out of 23 clusters, including E3 (IRS2, KRT6A), E5 (CD24, STMN1), E8 (GKN1, MUC5AC), E9 (PHGR1, TFF3), E10 (TFF3, TPO) and E13 (VTN and ITIH5)." (PMID 36333338, 2022).
respiratory disease (1 paper, 2023). "The identified inter-alpha-trypsin inhibitor heavy chain 5 (ITIH5) gene was associated with bovine respiratory disease susceptibility." (PMID 37512987, 2023).
ITIH5 also shares sentences with these, for which no sentence is quoted: lung adenocarcinoma (3 papers); thyroid cancer (2); adrenocortical carcinoma (1); atopic dermatitis (1); cervical squamous cell carcinoma (1); chronic hepatitis B (1); colon adenocarcinoma (1); diffuse large B-cell lymphoma (1); follicular carcinoma (1); follicular thyroid adenoma (1); gastric cancer (1); hepatocellular carcinoma (1); inflammatory skin disease (1); intrahepatic cholangiocarcinoma (1); invasive ductal carcinomas (1); lung squamous cell carcinoma (1); lymphoma (1); non-small cell lung carcinoma (1); ovarian carcinoma (1); ovarian serous cystadenocarcinoma (1); prostate carcinoma (1); psoriasis (1).